EPCAM (epithelial cell adhesion molecule)
Diseases named in the same sentence as EPCAM in open-access papers (continued):
Sharing a sentence is not in itself a finding about the gene and the disease.
tumor (continued). "Co-staining of TLR2, -4, and -9 with the epithelial marker EpCAM clearly indicated TLR expressing tumor cells in primary tumor tissue of all UICC stages (data not shown)." (PMID 27941651, 2016). "To prove the tumor-forming capacities of EpCAM+ cells isolated from the blood of tumor-bearing mice, we cultured CTCs without prior EpCAM selection in vitro." (PMID 27029058, 2016). "We observed that the expression of 10 of 12 CSC-related markers (CD90, ALDH1, CK7, CK19, OCT4, SOX2, vimentin, nestin, CD13 and EpCam) was not significantly different between the tumor tissues and peritumoral tissues." (PMID 27329727, 2016). "Circulating tumor cells (CTCs) are routinely identified as cytokeratin (CK)-positive, epithelial cell adhesion molecule (EpCAM)-positive, and CD45-negative and are enriched based on EpCAM." (PMID 27878106, 2016). "Flow cytometry analysis of viable HRT-18 cells (EpCAM positive/Annexin negative ) revealed that the fraction of viable tumor cells significantly increased in ascites samples with high concentrations of sEpCAM and after addition of recombinant EpEX." (PMID 25947366, 2015). "The limitation of the cell search system is that circulating tumor cells that do not express the marker EpCAM and/or Cytokeratins 8, 18 and 19 will not be detected by the system." (PMID 26498594, 2015). "Tumor cells were predominantly CD44+/CD24- and CD49f+/EpCAM+." (PMID 26311223, 2015). "E-cadherin, a calcium-dependent single-span transmembrane glycoprotein, has been widely known as a tumor suppressor and a characterized molecular marker of EMT, and is an important epithelial cell adhesion molecule and signal transduction factor located in the epithelial tissue." (PMID 26702618, 2015). "Although widely used, it is recognized that EpCAM-based enrichment suffers from limitations, such as relatively low sensitivity and purity, partly due to the presence of EpCAM negative tumor cells." (PMID 26322014, 2015). "Although EpCAM, CD133, CD24 and CD44 were expressed in all three subpopulations of Li-7 cells in vitro, interestingly, they were expressed only in a very low proportion of tumor cells expressing CD13 in vivo." (PMID 25885470, 2015). "We combined RNA and protein detection of living cells by FACS to gate for epithelial cell adhesion molecule (EPCAM) positive tumor and benign cells, EPCAM/CD45 double negative mesenchymal cells and CD45 positive infiltrating lymphocytes." (PMID 25514598, 2015). "Viable, non-apoptotic tumor cells were analyzed through the use of antibodies specific for epithelial tumor cell markers (EpCAM and pan-cytokeratin), a viability dye (debris exclusion), and an activated-caspase-3 antibody." (PMID 25807104, 2015). "Moreover, tumor and adjoining-normal breast cells of the same patients showed distinct CD49f+/EpCAM+ progenitor, CD271+/EpCAM- basal, and ALDEFLUOR+ cell profiles." (PMID 26311223, 2015). "The hFL-HCC tumour line had minimal expression of EpCAM and therefore was most similar to the more primitive EpCAM-negative hBTSC subpopulations." (PMID 26437858, 2015). "EpCAM differences between tumor patients and controls were also not apparent in the present investigation, which is in line with other reports." (PMID 25967040, 2015). "We posited that specific EpCAM-negative CTCs subpopulations, shed from the primary tumor and found in the circulation, avoid organ arrest with extreme efficiency by the concomitant presence of stem cell and quiescence properties." (PMID 26631983, 2015). "Some reports elucidating EpCAM-regulated downstream signaling molecules, such as E-cadherin and Wnt/β-catenin may help explain our founding on MTA1 and EpCAM modulation to promote tumor invasion and migration." (PMID 26698569, 2015). "K7, K19, EpCAM and OV6 expression were present in the membrane and cytoplasm of tumor cells." (PMID 26311117, 2015).
tumor (continued). "Several studies investigated expression of the full length EpCAM protein in PCa and tumor stroma, however none of these studies have correlated the expression of this protein with GS." (PMID 25695234, 2015). "In conclusion, regardless of cellular heterogeneity, inherited down-regulation or absence of CK and EpCAM or other tumor cell surface molecules, we obtained efficient detection of both CTCs and DTCs from mice or patients with diverse types of cancer." (PMID 26267323, 2015). "However, EpCAM-positive HCC cells were shown to have stem cell properties such as self-renewal, differentiation and tumor-initiating ability." (PMID 26165819, 2015). "Besides binding tumor cells via the EpCAM antigen and T-cells via the CD3 receptor, the intact Fc region of Catumaxomab recruits accessory cells to enhance the immune response against the tumor." (PMID 24757499, 2014). "Collectively, our findings suggest that KIAA1114high HCCs recapitulate some of the basic but essential features of existing liver TICs, including enhanced capacities for proliferation, self-renewal, and in vivo tumor generation, as those exhibited by CD133+ and EpCAM+ cells." (PMID 24713374, 2014). "The multifunctional antibody catumaxomab binds both to the EpCAM tumor cell antigen and to CD3+ lymphocytes, enhancing antitumor activity by redirecting T-cells and Fcgamma receptor I/III-positive accessory cells to the tumor." (PMID 25331657, 2014). "The use of EMT markers, e.g., vimentin, facilitated the capture of EpCAM/CK double-negative tumor cell in peripheral blood." (PMID 24886394, 2014). "Immunohistochemical analysis revealed that entire tumor area (but not tumor stroma) expressed high levels of the membrane-localized EpCAM." (PMID 24921652, 2014). "Methods using EpCAM as the tumor cell selection marker will not detect sub-populations of CTCs that have undergone EMT or lost EpCAM expression by other mechanisms." (PMID 24860781, 2014). "Because tumor cells from patients 2319 and 2334 were negative for EpCAM, it was difficult to calculate their precise tumor load." (PMID 24515916, 2014). "Lastly, the immunophenotype of tumor cells as C-KIT+/EpCAM+/E-cadherin+/K7−/K19−/CD56−/CD133− did not fit into any description of putative stem cell tumors of the liver." (PMID 25202388, 2014). "The results of preclinical study showed superior sensitivity of their system in detecting EpCAM-negative tumor cells in direct comparison with the standard method." (PMID 24886394, 2014). "The possibility to target multiple relevant cell types within the same tumor might compensate for the relatively low overexpression on malignant cancer cells compared with other tumor markers, like EGFR, Her2/Neu or EpCAM." (PMID 24742002, 2014). "Studies utilizing cell lines have established the limitation of EpCAM + selection in recovering basal-like tumor cell lines, although no definitive study has clearly illustrated that this type of enrichment is not successful in basaloid tumors." (PMID 24602188, 2014). "EpCAM is an epithelial marker that is present on epithelial tumor cells, but absent in most blood cells." (PMID 25222669, 2014). "Immunohistochemical staining showed that the tumor cells were positive for the hepatic stem cell markers C-KIT and epithelial cell adhesion molecule (EpCAM), and the epithelial cell markers epithelial membrane antigen (EMA), E-cadherin and β-catenin, and negative for hepatic and biliary markers." (PMID 25202388, 2014). "Due to the lack of a general marker, tumor cells are characterized as epithelial cells which are positive, among others, for EpCAM or cytokeratins." (PMID 24895575, 2014). "Although the epithelial cellular adhesion molecule (EpCAM) is the most used tumor surface biomarker in the detection of CTCs, it is not necessarily expressed in all types of epithelial tumor." (PMID 25258614, 2014).
tumor (continued). "Additionally, replating assays and immunocytochemical analyses of EpCAM and AFP indicated that GPC3 regulated tumor-initiating HCC cells." (PMID 24454751, 2014). "Tumor cells of the intermediate cell subtype of c-HCC-CCs express hepatocytic markers (AFP or HepPar-1), biliary markers (K7 or K19) and/or putative stem cell markers (CD56, CD133 or EpCAM)." (PMID 25202388, 2014). "Because CD166 is expressed in various types of cells, we used epithelial cell adhesion molecule (EpCAM), which is expressed exclusively in epithelia and epithelial-derived neoplasms, to exclude non-epithelial tissue from the analysis." (PMID 25221999, 2014). "As expected, the EpCAM negative fraction (containing only mouse stroma cells) did not initiate tumor growth." (PMID 25419568, 2014). "Tumor spheroid cells were continually cultured in vitro over the past 2.5 years without showing a significant change in CD133/EpCAM expression levels or signs of senescence." (PMID 23826249, 2013). "Immunohistochemistry stainings disclosed no changes in Ki67, CD44s, CD44v6, or EpCAM once tumours were formed by either cell type." (PMID 23150174, 2013). "Consistent with the pathological findings, flow cytometric analysis of xenograft tumors clearly demonstrated that metformin markedly reduced the number of tumor-initiating EpCAM+ cells, whereas sorafenib did not." (PMID 23922888, 2013). "Interestingly, both of our aptamers were able to successfully detect EpCAM in FFPE sections of a xenograft tumor of MDA-MB-231, while the EpCAM antibody showed negligible staining, demonstrating the higher sensitivity of our aptamers." (PMID 23460885, 2013). "These real-time PCR data are consistent with those of the RNA-seq analysis, and suggest that the human compartment of CXs only expresses the subset of immunotherapy target genes that are expressed in the EPCAM+ but not EPCAM− cells of the parental tumor." (PMID 24278200, 2013). "Double staining showed that EpCAM and PCNA were co-expressed in numerous tumor cells." (PMID 23251255, 2013). "RT-qPCR analysis on elderly HCCs demonstrated that the high expression levels of 7 putative hepatic stem/progenitor cell biomarkers (including keratin 19 (K19), ABCG2, CD44, Nestin, CD133, EPCAM and OV6), is related to tumor angiogenesis and a poor prognosis for the HCC." (PMID 24160375, 2013). "Both tumour samples similarly expressed CD44s and did not display any reactivity for CD44v6 and EpCAM." (PMID 23150174, 2013). "As a result, both epithelial tumor cells expressing low levels of EpCAM and cells with a mesenchymal phenotype lacking EpCAM were captured simultaneously from the same sample." (PMID 23634290, 2013). "Injecting 300 of the EpCAM+/CD45− cells in NOD/SCID mice induced tumor formation in 50% of the animals, but injection of 10,000 EpCAM−/CD45− did not." (PMID 24305653, 2013). "After >10 passages, the majority of the PPT2 cells expressed cell surface markers commonly used for the isolation of tumor-initiating cells from different types of human cancer, including CD133, CD44, CD44v6, EpCAM, CD166, CD49f, and presently, they retain these features after more than 26 passages." (PMID 24086245, 2013). "Therefore, we particularly focused on sunitinib resistance and performed immunohistochemical experiments on tumor samples to validate the discriminatory potential of four new candidate biomarkers, LGALS8, RAB17, EpCAM, and CD9." (PMID 23555683, 2013). "So far, the exact mechanisms of EpCAM contributing to the malignant potential of tumor cells are not entirely understood." (PMID 23830302, 2013). "In the remaining two tumors, no biallelic EPCAM deletions were observed, and the allelic profile obtained for the EPCAM gene region was identical in DNA isolated from tumor tissue and matched blood samples." (PMID 23938213, 2013).
tumor (continued). "Despite the higher percentages of CD133+/EpCAM+ cells in the cultured CSC population, the percentage of CD133+/EpCAM+ cells in the xenograft tumors declined to 4–6%, which is consistent with the percentage of CD133+/EpCAM+ cells observed in the original patient tumor." (PMID 23826249, 2013). "In other cancers, the use of EpCAM- or cytokeratin-based methods does not permit this differentiation, given that most patients with benign inflammatory diseases have an excellent prognosis and will not develop cancer." (PMID 23690774, 2013). "Mainly the failure to include tumor cells that have reduced or absent cytokeratin and/or EpCAM expression and the failure to identify such cell types limit investigations into additional tumor types." (PMID 23653529, 2013). "The EpCAM aptamer (EpDT3) but not the scrambled aptamer (Scr-EpDT3) bound to RB tumor cells, the Y79 and WERI-Rb1 cells." (PMID 23213278, 2012). "No colonies formed by day 7 after plating of the 165 EpCAM-positive cells isolated from MCF7 control samples or tumor-free controls." (PMID 22632416, 2012). "After 72 h of incubation, we observed increased levels of IFN-γ, TNF-α, IL-10, IL-2, and TGF-β1 in the supernatant of RB tumor cell and PBMC cultures incubated with 1 μg/ml of EpCAM×CD3 antibody compared to an incubation with CD3 or EpCAM monoclonal antibodies alone." (PMID 22328825, 2012). "Furthermore we studied the effect of GSI treatment on Notch downstream target Hes1 and tumor initiating cell markers CD44 and EpCAM in sorted CD44+/EpCAM+ cells." (PMID 23094026, 2012). "Cancer cells with epithelial phenotype need EpCAM as a growth- and invasion-promoting factor, whereas tumor cells with a mesenchymal phenotype are independent of EpCAM in invasion processes and tumor progression." (PMID 23110550, 2012). "The use of antibody mixtures and CE showed that additional EpCAM-negative and CK-negative tumor cells were present in peripheral blood." (PMID 21577258, 2011). "Interestingly, exposure to PGE2 before CM collection significantly augmented the ability of tissue sample A to increase the percentage of CD44+/CD24−/EpCAM+ cells, suggesting that PGE2 enhanced fibroblast tumor promoting ability." (PMID 21957456, 2011). "This has also imposed a clear bias on the study of CTCs, primarily the failure to include tumor cells that have reduced or absent CK and/or EpCAM." (PMID 21577258, 2011). "Surprisingly, the use of IMS with an anti-EpCAM antibody and ICC with anti-cytokeratin antibodies for detection of tumour cells resulted in minimal detection overlap, although results obtained with each method were associated with outcome in distinct prognostic subgroups of CRC patients." (PMID 21448171, 2011). "In this study we sought to compare two sensitive methods that both seek to identify tumor cells in sentinel lymph nodes, immunomagnetic selection (IMS) using antibodies targeting the epithelial surface proteins EpCAM and Mucin 1, and RT-PCR targeting breast-epithelial transcripts." (PMID 21816090, 2011). "This infers that in more than half of the metastatic patients, tumour cells were either not present in BM at diagnosis, or EpCAM and cytokeratin expression levels were below the detection limit of the respective method." (PMID 21448171, 2011). "Median (range) NCN (×1000) for EpCAM was 11800.1 (4357.7 - 39142.8) versus 7552.5 (475.2 - 13765.5) in tumour and non-tumoural surrounding pancreatic tissue respectively (p = 0.014)." (PMID 21281486, 2011). "EpCAM (p = 0.0001), IL8 (p = 0.0003), MIP-1β (p = 0.0026), MIP-3α (p = 0.039) and TIMP1 (p = 0.0017) levels were significantly different (Mann Whitney U test) between tumours versus AN & PN." (PMID 21092330, 2010). "EpCAM (p = 0.0001), IL8 (p = 0.0003), CCL4/MIP-1β (p = 0.0026), CCL20/MIP-3α (p = 0.039) and TIMP1 (p = 0.0017) tissue protein levels were significantly different (Mann Whitney U test) between tumours versus AN & PN." (PMID 21092330, 2010).
tumor (continued). "Decreased membranous EpCAM staining throughout the tumour rather than just at the invasive margin also correlates with increased risk of local recurrence, but is not indicative of distant recurrence." (PMID 21339979, 2010). "EpCAM (epithelial cell adhesion molecule) is not a perfect marker for CTC detection due to the high variation in its gene expression between tumor subtypes and its illegitimate transcription from leukocytes." (PMID 21129172, 2010). "Additionally, EpCAM (p = 0.0004), IL8 (p = 0.0015) and MIP-1β (p = 0.0061) were significantly elevated in tumours compared to their corresponding PN." (PMID 21092330, 2010). "Since we found that tumor-infiltrating leukocytes expressed high levels of ALDH1, we first separated ascites cells by CD326 (EpCAM, an epithelial marker to gate the tumor cell population) or CD45 (a lymphocyte maker to gate lymphocyte population) after removing dead cells using magnetic beads." (PMID 20422001, 2010). "Here, we explored whether human T cells that are redirected via an EpCAM/CD3-bispecific antibody called MT110 can lyse colorectal TICs and prevent tumor growth from TICs." (PMID 20976159, 2010). "Of 13 tumour samples, 9 comprised of CD133+ sub-populations representing >20% of epithelial cells co-staining for EpCAM, with one late-stage tumour (case 12) exhibiting CD133 expression on 85% of the EpCAM+ population." (PMID 20332776, 2010). "Moreover, the established CSQT-2 cells also showed varied expression of tumour-initiating cell (TIC) markers such as CD133, CD90 and EpCAM." (PMID 20461085, 2010). "EpCAM, IL8, CXCL10/IP10, CCL3/MIP-1α, CCL4/MIP-1β, CCL15/MIP-1δ, PDGFR-B protein were found to be expressed predominantly in tumours only, suggesting that they could be involved in the later stages of gastric tumorigenesis." (PMID 21092330, 2010). "Loss of membranous E-cadherin, CD44, CD44v6, EpCAM and CD166 expression have all been reported and often are not expressed within tumor budding cells themselves." (PMID 21317460, 2010). "In this study, the immunobead RT-PCR method, combining pre-analytical enrichment with magnetic beads coated with the EpCam-specific BerEP4 antibody with RT-PCR amplification of a panel of four markers, was optimised for the detection of circulating HNSCC tumour cells in peripheral blood samples." (PMID 19961621, 2009). "Similar results were reported in bone marrow samples involving a total of 26 CK+ tumor cells, of which none of them co-expressed EpCAM after chemotherapy." (PMID 18687126, 2008). "Since EpCAM is not equally expressed in all tumor cells, ideally, it would make better sense to use the same antibodies to enrich and identify CTCs." (PMID 18687126, 2008). "Another topic of the symposium was the question why EpCAM expression had in some tumour types a negative, in most a seemingly neutral and in other tumour types, a positive prognostic impact on the overall survival of patients." (PMID 17211480, 2007). "Intriguingly, loss of CD9 expression correlates with metastasis and, as reported at the symposium, a strict co-localisation of CD9 and EpCAM, as seen for membranes of normal colonic epithelium, was no longer found for tumour cell membranes." (PMID 17211480, 2007). "A comprehensive study of the temporal expression of EpCAM during tumour progression is currently lacking." (PMID 17325709, 2007). "This is the first fully human and functional fusion protein consisting of an scFv against epithelial cell adhesion molecule and human enzyme β-glucuronidase for future use in tumour-specific activation of a non-toxic glucuronide prodrug." (PMID 11875747, 2002). "Notably, EpCAM levels increased specifically in non-PCR patients, suggesting persistent tumor-derived EV release, whereas SSEA-4 levels increased only in patients who achieved pCR." (PMID 41514466, 2026).